CACYBP (calcyclin binding protein)
Description:
May be involved in calcium-dependent ubiquitination and subsequent proteasomal degradation of target proteins. Probably serves as a molecular bridge in ubiquitin E3 complexes. Participates in the ubiquitin-mediated degradation of beta-catenin (CTNNB1).
Synonyms: S100A6BP; SIP; PNAS-107; GIG5
Tractability: Small molecule: a structure with a bound ligand is known. PROTAC: ubiquitination databases record sites on it; its protein half-life has been measured.
Gene: Protein-coding gene on chromosome 1 (174,999,163 to 175,012,027, forward strand). Ensembl gene ENSG00000116161.
Subcellular location: Nucleus; Cytoplasm
Subcellular location (Human Protein Atlas): Cytosol; Nucleoplasm
Gene Ontology:
Molecular function: protein binding; protein homodimerization activity; molecular adaptor activity; ubiquitin protein ligase binding; protein domain specific binding; S100 protein binding; tubulin binding
Biological process: heart development; cardiac muscle cell differentiation; cellular response to calcium ion; positive regulation of DNA replication; response to growth hormone
Cellular component: beta-catenin destruction complex; cytosol; extracellular exosome; nucleoplasm; nucleus; SCF ubiquitin ligase complex; cell body; cytoplasm; nuclear envelope lumen
Genetic constraint (gnomAD): Loss-of-function variants: 7 observed, 9.06 expected, observed/expected ratio (o/e) 0.77, 90% interval 0.44 to 1.44. That is too few expected variants to judge how well the gene tolerates losing a copy. Missense variants: 81 observed, 103.31 expected, observed/expected ratio (o/e) 0.78, 90% interval 0.65 to 0.94. Synonymous variants: 31 observed, 34.57 expected, observed/expected ratio (o/e) 0.9, 90% interval 0.67 to 1.21.
Homologues: Orthologues: chimpanzee CACYBP (100% identical), macaque CACYBP (99% identical), dog CACYBP (98% identical), pig CACYBP (97% identical), mouse Cacybp (93% identical), rat Cacybp (91% identical), tropical clawed frog cacybp (71% identical), zebrafish cacybp (60% identical), Drosophila melanogaster CG3226 (38% identical).
Diseases named in the same sentence as CACYBP in open-access papers:
CACYBP is named in the same sentence as 56 diseases in open-access papers, as found by Europe PMC text mining. Sharing a sentence is not in itself a finding about the gene and the disease. The quoted sentences say what the papers report.
gastric cancer (13 papers, 2010 to 2025). A primary or metastatic malignant neoplasm involving the stomach. "On the contrary, some reports found that CACYBP expression was reduced in gastric cancer and renal cancer." (PMID 36576589, 2023). "Similar tumor-suppressory effect of CacyBP/SIP was stated in studies on gastric cancer, breast cancer and astrocytoma." (PMID 33330038, 2020). "We also showed that S100 proteins negatively regulate CacyBP/SIP-mediated inhibition of gastric cancer cell proliferation, through an effect on β-catenin protein expression and transcriptional activation of Tcf/LEF." (PMID 22295074, 2012). "Another team studied the expression profile of CacyBP/SIP in 181 cases of gastric cancer." (PMID 34179100, 2021). "However, previous data from our lab demonstrated that overexpression of CacyBP/SIP inhibits the growth of renal carcinoma cells and gastric cancer cells, suggesting that CacyBP/SIP has tumor-specific roles, similar to SIRT1, NF-κB, and TGF-beta." (PMID 28196083, 2017). "Calcyclin-binding protein was also a member of that functional group, and its expression has been correlated with resistance to chemotherapy in gastric cancer and positively correlated with the expression of nestin (NES) and the prognostic 80-gene expression profiling (GEP80) model in MM." (PMID 27527861, 2016). "CACYBP is also reported to be under expressed in gastric cancer and renal cancer." (PMID 21114830, 2010). "Notably, CACYBP’s role in gastric cancer, glioma, and breast cancer remains controversial." (PMID 40167359, 2025). "Numerous studies have highlighted the aberrant expression of CACYBP in several malignant cancers like glioma, breast cancer (BC), gastric cancer (GC), colon cancer and pancreatic cancer." (PMID 37305391, 2023). "Importantly, cells transfected with CacyBP/SIPΔS100 exhibited more intense effects relative to wild-type transfectants, suggesting that S100 proteins might negatively regulate the inhibition of cell proliferation induced by CacyBP/SIP in gastric cancer cells." (PMID 22295074, 2012). "Despite this progress, the effects of S100 proteins on CacyBP/SIP in gastric cancer remain unclear." (PMID 22295074, 2012). "CACYBP has been reported as an independent prognostic factor in multiple cancers such as HCC and gastric cancer." (PMID 37077914, 2023). "KT regulated the expression of the calcyclin-binding protein (CYBP) and cathepsin K. CYBP has been reported as a negative regulator of malignant behavior in gastric cancer and metastasis in colon cancer." (PMID 36674719, 2023). "Interestingly, CACYBP could inhibit the proliferation of gastric cancer and renal cancer cells." (PMID 36576589, 2023). "Our group characterized a similar translocation of CacyBP/SIP from the cytosol to the nucleus in colon cancer cell lines and gastric cancer cells, following treatment with gastrin, which also changed the [Ca2+]i." (PMID 29534068, 2018). "Particularly, gastrin stimulates the nuclear translocation of CacyBP/SIP, which was also correlated with the elevation of [Ca2+]i and stimulated proliferation of gastric cancer." (PMID 28196083, 2017). "In a previous report, CacyBP/SIP, which was expressed at a relatively low level in MKN45 cells, was widely expressed in several different types of gastric cancer cell lines." (PMID 22295074, 2012). "Our previous studies also showed that CacyBP/SIP inhibits growth and proliferation of gastric cancer cells partly via degradation of β –catenin." (PMID 22295074, 2012). "Similarly, the calcium-binding protein/Siah-1 interacting protein (CacyBP/SIP) has been found to inhibit cell growth and invasion in gastric cancer cells by activating β-catenin expression and Tcf/LEF transcription." (PMID 38370477, 2024). "Calcyclin-binding protein (CacyBP/SIP), identified on the basis of its ability to interact with S100 proteins in a calcium-dependent manner, was previously found to inhibit the proliferation and tumorigenesis of gastric cancer cells in our laboratory." (PMID 22295074, 2012).
gastric cancer (continued). "Therefore, the truncated mutant CacyBP/SIP was named CacyBP/SIPΔS100 and provides a useful tool for investigation of the effects of S100A6 on the biological behavior of CacyBP/SIP in gastric cancer cells." (PMID 22295074, 2012). "Calcyclin-binding protein (CacyBP/SIP), a 30 kDa protein identified on the basis of its ability to interact with S100A6 in a Ca2+-dependent manner in Ehrlich ascites tumour (EAT) cells, was previously thought as a multiple-drug resistance (MDR)-related molecule in gastric cancer in our laboratory." (PMID 22295074, 2012). "However, in the study by Ning, the eukaryotic expression vectors of wild-type CacyBP (FLAG-CacyBP) and a truncated mutant lacking the NLS domain (FLAG-CacyBPΔNLS) were constructed and transfected into MKN45 gastric cancer cells." (PMID 29534068, 2018).
colon cancer (12 papers, 2014 to 2025). "In colon cancer, CACYBP enhances proliferation by interacting with Skp1 to degrade p27ˆKip1, while in cholangiocarcinoma, it promotes progression by inhibiting MCM2 ubiquitination and activating the Wnt/β-catenin signaling pathway." (PMID 40167359, 2025). "SNRK expression was found to be decreased in human colon cancer tissues, while overexpression of SNRK inhibited colon cancer cell proliferation by upregulating calcyclin-binding protein (CacyBP) and promoting β-catenin degradation." (PMID 41141622, 2025). "Overexpression of CacyBP in primary colon cancer cell lines showed downregulated levels of cellular β-Catenin and significant reduction in cellular adhesion." (PMID 39195316, 2024). "In colon cancer, CacyBP can promote the growth of cancer cells by enhancing the ubiquitin-mediated degradation of p27kip1." (PMID 33541291, 2021). "Mechanistically, SNRK inhibits the proliferation of colon cancer cells through upregulation of calcyclin-binding protein (CacyBP) and β-catenin degradation." (PMID 32968716, 2020). "Preliminary results showed that colon cancer SW480 cells express more endogenous CacyBP/SIP protein than HT 29 cells and lovo cells." (PMID 29534068, 2018). "And we confirmed that CacyBP/SIP was also re-translocated from the nuclei to the cytoplasm by decreasing the intracellular [Ca2+]i with BAPTA in colon cancer SW480 cells." (PMID 29534068, 2018). "In summary, we showed that S100A6 is involved in the nuclear translocation of CacyBP/SIP in a Ca2+-dependent manner in colon cancer SW480 cells." (PMID 29534068, 2018). "Our group has generated a monoclonal antibody against CacyBP/SIP and, using this specific antibody and immunohistochemistry, has shown that CacyBP/SIP is over-expressed in colon cancer tissue and is mainly localized in the nucleus." (PMID 29534068, 2018). "For example, CACYBP in the brown module correlates with proliferation and metastasis in colon cancer as well as drug resistance in pancreatic cancer." (PMID 29371966, 2017). "We cultured human colon cancer cells, stimulated their proliferation with the carcinogen gastrin and examined the intracellular distribution of CacyBP/SIP." (PMID 28196083, 2017). "To study the role of CacyBP/SIP in proliferation of colon cancer cells, we examined the effect of CacyBP/SIP knockdown on the cell proliferation under either basal condition or treatment with gastrin, a hormone known to trigger colon cancer." (PMID 28196083, 2017). "CacyBP/SIP promoted the cell proliferation of colon cancer cells under both basal and gastrin stimulated conditions as shown by knockdown studies." (PMID 28196083, 2017). "The present work not only confirmed this finding with a large set of samples, but also demonstrated an important role for CacyBP/SIP in promoting proliferation of human colon cancer." (PMID 28196083, 2017). "This is also supported by analysis of the relative abundance of nuclear and cytoplasmic CacyBP/SIP in colon cancer cells by Western blotting before and after 10−8 mol/L gastrin stimulation for 8 h." (PMID 28196083, 2017). "Knockdown of CacyBP/SIP retarded the growth of colon cancer cells under both basal and gastrin-treated conditions." (PMID 28196083, 2017). "In this study, we tested the hypothesis that S100 proteins are involved in the nuclear translocation of CacyBP/SIP following the elevation of intracellular Ca2+ concentration in colon cancer SW480 cells." (PMID 29534068, 2018). "Thus, we confirmed that the effect of ionomycin on the subcellular distribution of CacyBP/SIP is due to the change in intracellular [Ca2+]i in colon cancer SW480 cells." (PMID 29534068, 2018). "Another question is whether the behavior and effects of CacyBP/SIP observed here are specific to colon cancer or whether they also apply to other types of cancer." (PMID 28196083, 2017). "This supports the hypothesis that CacyBP/SIP expression levels may positively correlate with colon cancer." (PMID 28196083, 2017).
colon cancer (continued). "In particular, colon cancer cells showed high levels of CacyBP/SIP expression." (PMID 28196083, 2017). "To examine whether CacyBP/SIP promotes colon cancer cell proliferation, we reduced the expression of CacyBP/SIP using short interfering (si) RNA." (PMID 28196083, 2017). "Therefore, CacyBP/SIP overexpression is also functionally related to the colon cancer growth." (PMID 28196083, 2017). "It is unknown whether CacyBP/SIP promotes the proliferation of colon cancer cells." (PMID 28196083, 2017). "Recently, it was reported that CacyBP/SIP could play an important role in colon cancer." (PMID 22926504, 2014). "Co-immunoprecipitation was used to examine the interaction of endogenous CacyBP/SIP with S100A1 and S100A6 in colon cancer SW480 cells." (PMID 29534068, 2018). "In this study, we demonstrated that in colon cancer SW480 cells, CacyBP/SIP was translocated from the cytoplasm to the nuclei in response to elevated intracellular Ca2+ by ionomycin." (PMID 29534068, 2018). "Previously we showed that CacyBP/SIP is expressed at high levels in several cancers, including colon cancer." (PMID 28196083, 2017). "CacyBP/SIP expression was detected in the cytoplasm and/or nucleus of 51% of colon cancer tissue (17 of 33), compared to only 19% of adjacent tissue (5 of 26; p < 0.05)." (PMID 28196083, 2017). "Moreover, SNRK increased CacyBP mRNA and protein and decreased β-catenin protein in HCT116 and RKO colon cancer cells." (PMID 40149719, 2025). "Our previous work showed that CacyBP/SIP is overexpressed in colon cancer tissue compared to normal tissues." (PMID 28196083, 2017). "Inversely, CACYBP could promote tumor progression by regulating apoptosis, cell proliferation and invasion and arresting the cell cycle in many cancers, such as hepatocellular carcinoma (HCC), colon cancer and osteosarcoma." (PMID 36576589, 2023).
hepatocellular carcinoma (9 papers, 2019 to 2025). A malignant tumor that arises from hepatocytes. "High expression of CACYBP in hepatocellular carcinoma patients with poor prognosis is required for hepatocellular carcinoma cell growth both in vitro and in vivo." (PMID 40564276, 2025). "Recent studies have reported that MyD88 is a novel downstream substrate of CacyBP in hepatocellular carcinoma." (PMID 38785969, 2024). "In hepatocellular carcinoma, CACYBP could regulate cancer cell growth, apoptosis and cell cycle, thereby accelerating tumor progression, and CACYBP overexpression also predicted a poor prognosis." (PMID 37305391, 2023). "Inhibition of the binding of CacyBP-MyD88 could reduce fractalkine (CX3CL1) secretion and thus weaken the recruitment of tumor-associated macrophages (TAMs) to the immune microenvironment, making hepatocellular carcinoma mice sensitive to programmed death 1 (PD-1) treatment." (PMID 38785969, 2024). "In terms of CACYBP, it has been verified that CACYBP can promote hepatocellular carcinoma progression in the absence of RNF41-mediated degradation." (PMID 33014055, 2020). "BIRC5, SPINK5, SPP1, CACYBP, RAET1E, and NR0B1 were significantly up-regulated, and S100A8 was significantly down-regulated in hepatocellular carcinoma samples based on TCGA-HCC dataset." (PMID 33568167, 2021).
pancreatic cancer (8 papers, 2014 to 2025). "Among them is pancreatic cancer, in which CacyBP/SIP expression is associated with an aggressive phenotype." (PMID 22926504, 2014). "It was reported that CacyBP/SIP was significantly increased in pancreatic cancer and bladder cancer." (PMID 36576589, 2023). "Similarly, CACYBP knockdown in pancreatic cancer inhibits cell growth by blocking the G1-to-S phase transition, mediated by the downregulation of Cyclin E, Cyclin A, and CDK2, along with the upregulation of p27ˆKip1 and Rb." (PMID 40167359, 2025). "A comprehensive pan-cancer analysis identified CACYBP as being upregulated in 14 cancers—including lung, liver, colon, pancreatic cancers, and cholangiocarcinoma—while it was downregulated in six cancers, such as kidney renal clear cell carcinoma and prostate cancer." (PMID 40167359, 2025). "Previous studies have suggested that overexpression of CacyBP/SIP might inhibit drug-induced apoptosis by enhancing the Bcl-2/Bax ratio in pancreatic cancer cells (Xiong Chen, Apoptosis 2013)." (PMID 30234028, 2018). "We have detected CacyBP/SIP in many types of tumor tissues, and it is overexpressed in nasopharyngeal carcinoma, osteogenic sarcoma, and pancreatic cancer." (PMID 28196083, 2017). "Another study confirmed that CacyBP/SIP is not detected in normal pancreatic tissues but is detected in pancreatic cancer." (PMID 25799022, 2015).
renal carcinoma (8 papers, 2010 to 2025). A carcinoma arising from the epithelium of the renal parenchyma or the renal pelvis. "In renal cancer, CACYBP overexpression reduces Cyclin D1 levels through β-catenin degradation, thereby inhibiting cell growth and tumorigenicity—further supporting its tumor-suppressive role." (PMID 40167359, 2025). "In renal cancer, the expression of CACYBP/SIP protein was significantly decreased in renal cancer tissues and renal cancer cell lines." (PMID 34179100, 2021). "Previous studies have reported that CACYBP contributes to the development of a wide range of human malignancies, including gastric, pancreatic, colon, breast, brain, and renal cancer." (PMID 34746138, 2021). "However, in renal cancer and chronic lymphoblastic leukemia, the expression of CacyBP/SIP is decreased, which plays a role in tumor inhibition." (PMID 34179100, 2021). "CACYBP can suppress proliferation and tumorigenesis of renal cancer cells." (PMID 21114830, 2010). "In conclusion, literature data and the results of our own research suggest that the expression of CacyBP/SIP depends on the type and histological grade of renal cancer." (PMID 37373509, 2023). "Several studies have shown that CacyBP/SIP was notably overexpressed in pancreatic, colorectal, and breast cancer, while it was strongly decreased in gastric and renal carcinoma, where it was considered as a tumor suppressor." (PMID 36042446, 2022). "Through use of a monoclonal antibody against CacyBP/SIP, we have shown that overexpression of CacyBP/SIP inhibits the proliferation and tumorgenesis of renal cancer cells." (PMID 22295074, 2012).